ENSG00000221300
Synonyms: LOC124900542
Gene: Small nucleolar RNA gene on chromosome 2 (42,440,377 to 42,440,436, forward strand). Ensembl gene ENSG00000221300.
Gene Ontology:
Biological process: RNA processing
Cellular component: nucleolus
Homologues: Orthologues: rat LOC120096422 (65% identical), zebrafish snord75.1 (63% identical), mouse Gm56367 (62% identical), rat LOC120103353 (62% identical).